CD300E (CD300e molecule)
Diseases named in the same sentence as CD300E in open-access papers (continued):
Sharing a sentence is not in itself a finding about the gene and the disease.
tumor (5 papers, 2020 to 2024). "By further analyzing CD300E through bioinformatics and cellular biology experiments, we aim to explore and demonstrate its role in tumor development and progression." (PMID 39144140, 2024). "In the realm of oncology, the study of CD300E is garnering increasing attention due to its potential role in modulating tumor immune responses and facilitating immune escape." (PMID 39144140, 2024). "Analysis of differentially expressed genes revealed significant downregulation of CD300E in the exercise group, indicating its role in tumor growth regulation, particularly within an active context." (PMID 39144140, 2024). "These trials should include a variety of exercise regimens from moderate to high intensity and monitor changes in CD300E expression, tumor progression, and clinical prognosis." (PMID 39144140, 2024). "From the heatmap, it is evident that CD300E’s correlations with various immune cells vary, illustrating the heterogeneity of tumor microenvironments." (PMID 39144140, 2024). "CD300E notably suppresses oxidative stress pathways, potentially facilitating conditions favorable for tumor growth." (PMID 39144140, 2024). "The increased expression of CD300E resulted in both Immunosuppressive and immunopromoting cells, affecting the tumor microenvironment, which could potentially affect the prognosis and the degree of response to immunotherapy." (PMID 39144140, 2024). "This suggests that elevated expression of CD300E may foster an immunosuppressive state conducive to tumor growth and metastasis." (PMID 39144140, 2024). "Moreover, the study focuses predominantly on the role of a single gene, CD300E, while tumor development involves multiple genes and signaling pathways interacting." (PMID 39144140, 2024). "Furthermore, overexpression of CD300E significantly promotes the migratory and invasive capabilities of these tumor cells, whereas its inhibition reduces these properties." (PMID 39144140, 2024). "Moreover, we recommend longitudinal studies to track CD300E expression and tumor progression in response to sustained exercise therapy." (PMID 39144140, 2024). "Increased CD300E expression might enhance the functionality of Tregs, thereby fostering an immune-suppressive tumor microenvironment favorable for tumor survival and progression." (PMID 39144140, 2024). "Additionally, the relationship between tumor mutational burden (TMB) and CD300E expression was investigated, revealing a positive correlation in SARC, OV, COAD, BRCA, BLCA, and THYM, and a negative correlation in LAML, LIHC, and PAAD." (PMID 39144140, 2024). "Specifically, CD300E may promote tumor growth and dissemination by influencing the interactions between tumor cells and the immune system." (PMID 39144140, 2024). "Understanding the precise mechanisms of CD300E’s involvement in tumor immunity is critical for the development of novel immunotherapeutic strategies, which could include modulating its expression or function to enhance the immune system’s capacity to target tumors." (PMID 39144140, 2024). "In addition, the direct upstream transcription factor(s) by which exercise regulates CD300E expression in tumor cells remains unknown." (PMID 39144140, 2024). "Analysis of the relationships between CD300E and various immune cell subpopulations indicates that CD300E may influence tumor growth and immune escape by modulating immune cells within the tumor microenvironment, particularly immunosuppressive M2 macrophages and regulatory T cells." (PMID 39144140, 2024). "Therefore, we hypothesize that the ability of CD300E to promote tumor cell value-addition and migration is reached by regulating calcium channels." (PMID 39144140, 2024). "Singular Focus of Study Design: Although we observed the impact of exercise on tumor growth and CD300E expression, there is a lack of exploration into variables such as exercise intensity, frequency, and duration." (PMID 39144140, 2024).
tumor (continued). "For instance, the direct link between changes in CD300E expression and specific tumor behaviors has not been fully established." (PMID 39144140, 2024). "Additionally, CD300E significantly enhances pathways such as TNF-α signaling, inflammatory response pathways, IL6-JAK signaling, and epithelial-mesenchymal transition (EMT), all of which are documented to potentially promote tumor growth and metastasis." (PMID 39144140, 2024).
infection (1 paper, 2017). The state of being infected such as from the introduction of a foreign agent such as serum, vaccine, antigenic substance or organism. "Thinking about this evidence, we were impressed by the finding that the infection of macrophages by Hp seemed to revert the expression of CD300E." (PMID 29085364, 2017). "The exposure of macrophages to Hp resulted in a time-dependent accumulation of CD300E on the plasma membrane that, after 72 h of infection, was about 10 times over the level of mock cells." (PMID 29085364, 2017). "Notably, the activation of CD300E affected the antigen presentation independently from the infection, in accordance to the HLA-DR expression pattern." (PMID 29085364, 2017).
CD300E also shares sentences with these, for which no sentence is quoted: viral infection (2 papers); colorectal adenocarcinoma (1); diffuse large B-cell lymphoma (1); lung carcinoma (1); Myeloma (1); ovarian carcinoma (1); Type 1 Diabetes (1).